BRCA2 (BRCA2 DNA repair associated)
Diseases named in the same sentence as BRCA2 in open-access papers (continued):
Sharing a sentence is not in itself a finding about the gene and the disease.
cancer (continued). "Because BRCA2 mutation carriers typically develop cancers in certain epithelial tissues including the breast, ovary, pancreas, or prostate, we speculate that organ-specific differences in endogenous aldehyde accumulation or extrinsic exposure may account in part for the observed tissue selectivity." (PMID 28575672, 2017). "Therefore, DHC can potentially be used for sensitizing BRCA2-deficient cancer cells." (PMID 29215575, 2017). "Thus in cancer cells with BRCA2 mutation that already display a deficiency in DNA repair, inhibition of PARP1 activity leads to an accumulation of single strand breaks that are converted to double strand breaks that can not be repaired and result in cell death." (PMID 27488020, 2016). "In addition, one of the 9 active compounds, adenosine 5’-monophosphate (A5MP), and also its mimic 5-aminoimidazole-4-carboxamide ribonucleotide (AICAR) 5’ phosphate (ZMP) inhibited RAD52 activity in vivo and exerted synthetic lethality against BRCA1 and BRCA2–mutated carcinomas." (PMID 26784987, 2016). "Furthermore, SNPs at 8q12.1 near TOX were associated with HER2-positive cancer in BRCA2 carriers." (PMID 25919761, 2014). "Overall, the meta-analysis suggested that BRCA2 N372H may be a cancer susceptibility polymorphism." (PMID 25348552, 2014). "Human studies suggest that elevated PRA expression is generally associated with a poor prognosis, and there is evidence that genetic predisposition to cancer development due to mutations in BRCA1 or BRCA2 genes leads to PRA overexpression, which may play a role in disease progression." (PMID 25515784, 2014). "However, all of the patients in the TCGA cohort received platinum-based chemotherapy, and the beneficial effect of a BRCA1 or BRCA2 deficiency on OS may be due to improved treatment response, or due to the less lethal potential of mBRCA-associated cancers." (PMID 24265793, 2013). "Although some experiments raise the possibility that BRCA1-deficient cells may be resistant to anti-cancer agents targeting the microtubules (such as vinca alkaloids and taxanes), no preclinical in vivo studies have ever demonstrated taxane resistance in BRCA2-deficient cells." (PMID 20877358, 2010). "However, somatic mutations of BRCA2 are extremely rare in sporadic cancers." (PMID 9365162, 1997). "Another notable example was CKAP2L, which clusters together with several genes identified from referencing of our immunopeptidomics data, including BIRC5, BRCA2, and CENPF, forming a cluster of genes associated with cell proliferation across cancers." (PMID 41477871, 2026). "In contrast, BRCA2 was detected across various cancer types with 52.6% (10/19) classified as on-tumor." (PMID 40926019, 2026). "Treatment of cancers with specific DNA repair defects, including those harbouring BRCA1 or BRCA2 mutations." (PMID 41537447, 2026). "In the UK, cancer genetic testing is primarily conducted through targeted panels that focus on specific cancer types or known genetic mutations associated with particular cancers, such as BRCA1 and BRCA2 mutations for breast and ovarian cancers." (PMID 41206382, 2026). "Pathogenic or likely pathogenic variants in cancer-associated genes were identified in 37 (6.8%), most frequently in MITF, DICER1, and BRCA2, while 43 (7.9%) harbored variants in NDD-related genes, including DHCR7, POLG, and ARSA." (PMID 41844650, 2026). "In a prospective, multicenter cohort study involving 2,482 women with BRCA1 or BRCA2 mutations, researchers assessed the impact of risk-reducing mastectomy or BSO on cancer outcomes." (PMID 41488281, 2026).
cancer (continued). "Hence, our work reveals a previously unknown function of MDC1 in RF biology, a role that contributes to DNA damage induced by genotoxic agents and the response of BRCA1- or BRCA2-deficient tumors to clinically relevant anti-cancer drugs, such as PARPi and cisplatin." (PMID 41408464, 2026). "These insights deepen our understanding of how BRCA2-deficient tumors evolve, and offer alternate therapeutic opportunities, targeting A3B, UNG2, APE1, and the NF-κB axis, to suppress mutagenesis, delay resistance, and improve outcomes in BRCA2-mutant cancers." (PMID 41162355, 2025). "In the current Cancer Research UK-funded study called Precision HBOC, a SNP313 PRS is being used to stratify risk in BRCA1 and BRCA2 carriers." (PMID 40227593, 2025). "The most concordant cancer susceptibility genes represented in the combined data were BRCA1, BRCA2 and ATM, with 13, 11, and 6 pathogenic/likely pathogenic germline variants, respectively." (PMID 41465149, 2025). "For Latin American populations, while BRCA1 and BRCA2 PVs are well-known in hereditary breast and ovarian cancer syndrome (HBOC), other HCS associated with risks for cancers beyond breast and ovarian are less well-characterized." (PMID 40065011, 2025). "The need for supplementing PGS to BRCA2 PV status for more accurate risk assessment is evident by comparing the predicted probability from BRCA2‐only (open triangles) and BRCA2 + PGS (squares) with observed cancer prevalence (solid dots)." (PMID 40462315, 2025). "This approach was chosen due to the substantial differences in cancer risk profiles between BRCA2 and BRCA1, as well as the greater number of BRCA2 P/LP carriers in the UK Biobank, which allowed for increased statistical power." (PMID 40462315, 2025). "Beyond BC, BRCA1 and BRCA2 also play roles in other types of cancer, such as melanoma, pancreatic, prostate, biliary tract, esophageal cancer, and gastric cancer." (PMID 40071159, 2025). "In one case-control study of 63,828 patients with 14 common cancer types and 37,086 controls in Japan, pathogenic variants in BRCA1 were associated with biliary tract cancer, in BRCA2 with esophageal cancer, and in BRCA1/2 with gastric cancer." (PMID 39996890, 2025). "Positive lymphovascular invasion, a high Ki-67 index, multifocality, prior cancer history, and inheritance of germline gene variants such as BRCA1 and BRCA2 also contribute to a poorer prognosis." (PMID 40831739, 2025). "Evidence suggests that BRCA1 and BRCA2 are crucial targets for innovative canine cancer therapies, offering promising parallels to human medicine and underlining the importance of a comparative approach." (PMID 40004231, 2025). "Our findings highlight the therapeutic potential of splicing modulation to restore BRCA2 function in mutant cells, offering a promising strategy to prevent cancer development." (PMID 39741007, 2025). "Variants in BRCA1 and BRCA2 disrupt the HRR pathway, compromising the ability of cancer cells to repair platinum-induced DNA damage and thereby increasing their sensitivity to platinum-based chemotherapy." (PMID 40777133, 2025). "Studies have shown that loss of BRCA2 leads to cells being 100 to 1000 times more sensitive to PARPi, this led to their exploitation in the clinic in the context of BRCA1/2-mutated cancer." (PMID 41347092, 2025). "We also demonstrated that the penetrance of cancers in carriers of BRCA2 PVs increased significantly with higher cancer‐specific PGS deciles." (PMID 40462315, 2025).
cancer (continued). "The incidence rate of BRCA1 vs. BRCA2 PCa and other cancers was investigated through the Consortium of Investigators of Modifiers of BRCA1/2 (CIMBA), comprising data from 6902 men worldwide (33 countries)." (PMID 40002276, 2025). "Research has identified candidate genes associated with CMT development, including breast cancer gene 1 (BRCA1) and breast cancer gene 2 (BRCA2)." (PMID 40004231, 2025). "Individuals with biallelic pathogenic variants in FANCD1/BRCA2 and FANCN/PALB2 exhibit a unique cancer predisposition." (PMID 40970532, 2025). "Ever since the specific killing of BRCA1‐ or BRCA2‐deficient tumor cells by PARP inhibition was reported, several PARP inhibitors have been successfully developed and used for cancer therapy." (PMID 39462683, 2025). "These drugs are particularly effective in cancers that already have deficiencies in DNA repair mechanisms, such as those with mutations in the BRCA1 and BRCA2 genes." (PMID 40127955, 2025). "Among all cancers, both the germline and somatic mutation frequencies of BRCA1 or BRCA2 in HGSOC are the highest." (PMID 40830526, 2025). "When analyzed as continuous variable, HRD score in cancers with BRCA2 and ATM alterations was significantly higher than in those without identified HRR mutations." (PMID 41465280, 2025). "Of the 18 patients with mutations in the BRCA1 and BRCA2 genes, 14 had a family history (FH) of cancer; of the 7 patients with mutations in the ATM gene, 5 had a cancer FH, and of the 34 patients with other altered genes, 27 had a cancer FH." (PMID 40259910, 2025). "The groundbreaking aspect of using olaparib in human medicine for treating cancers with BRCA1 and BRCA2 mutations was demonstrated in patients with metastatic breast tumors that harbor BRCA1/2 mutations, achieving an overall response rate (OR) of 50%." (PMID 40004231, 2025). "PARP inhibitors have emerged as a major field of cancer therapy because of their function in DNA repair, especially for tumors containing BRCA1 and BRCA2 mutations." (PMID 40141415, 2025). "Together, BRCA1 and BRCA2 cooperate in a concerted effort to repair damaged DNA, regulate cell growth, and prevent cancer development by ensuring that the cell’s genetic material remains stable and intact." (PMID 40004231, 2025). "In the current study, we determined the GIS in association with the mutational status of BRCA1, BRCA2, and 20 other HRR‐related genes across 143 tumors from 24 cancer entities with HRR pathway alterations." (PMID 40278800, 2025). "This is likely due to a combination of factors such as relatively low penetrance for these cancers, rarity of BRCA2 PVs, and small sample size." (PMID 40462315, 2025). "Notable examples include the eukaryotic BRCA2 protein involved in various cancers, the DNA ligase 4, the archaeao-eukaryotic MCM replicative helicase, the bacterial DNA polymerase II, and the bacterial DNA repair RuvA protein." (PMID 41242521, 2025). "The genes BRCA1 and BRCA2 were targeted for knockout (KO) in lymphnode cancer of the prostate (cell line) [LNCaP] using clustered regularly interspaced short palindromic repeats (CRISPR)-Cas9 technology." (PMID 41236806, 2025).
cancer (continued). "Surveillance and risk-reducing surgeries are associated with >90% reduction in cancer incidence and significantly decreased cancer mortality for female BRCA1/BRCA2 carriers." (PMID 40745491, 2025). "Due to limited sample sizes for single gene alterations, similar phenomena were also observed for BRCA1 and BRCA2 in some cancers." (PMID 40420266, 2025). "Only two genes (BRIP1A and BRCA2) were included in the panel used in this study, and further analysis with a larger cancer panel is necessary to investigate these patients." (PMID 40554495, 2025). "Of known cancer susceptibility genes, some evidence of association was seen for ATM (p = 0.00012) and BRCA2 (p = 0.0025)." (PMID 39749474, 2025). "An interesting and practically important observation of our study was the relatively lower penetrance for core HBOC cancers among carriers of BRCA2 PVs than commonly estimated." (PMID 40462315, 2025). "Even though limited toxicity is induced, a clear effect on the RAD51 IRIF and BRCA2 protein levels was shown in the normal breast epithelial cell line (MCF10a) and the tested cancer cell lines." (PMID 40647408, 2025). "This is related to the growing importance of PARP inhibitors in cancer therapy, and the presence of BRCA1 or BRCA2 mutations is a good predictive marker that indicates the probable high effectiveness of PARP inhibitors in therapy." (PMID 40429755, 2025). "Collectively, these findings demonstrate that CldU and PARPi act synergistically in BRCA2-mutant cancer cells, even in the context of acquired PARP inhibitor resistance, including resistance mediated by BRCA2 reversion mutations." (PMID 41347092, 2025). "This is evidenced by the cancer predisposition associated with germline mutations in BRCA1, BRCA2, and other HR genes, as well as by the frequent somatic suppression of HR observed in sporadic cancers, where it acts as a driver of tumorigenesis." (PMID 41463247, 2025). "Interest in PARP inhibitors has increased since blocking PARP1 results in notable cell death in cancer cells with gene mutations, including BRCA1 and BRCA2." (PMID 40141415, 2025). "As the vast majority of variants reported in BRCA2 (3,341 in total) are VUS, this presents a major challenge for the clinical management of carriers, both healthy individuals and patients with cancer." (PMID 40232841, 2025). "Similar findings have been reported for other DNA repair genes, such as BRCA1 and BRCA2, which show tissue-specific effects in cancer prognosis." (PMID 40493574, 2025). "Specifically, one of their cases was BRCA2-positive and had a significant family history of cancer, but was still living 5.5 years post-initial diagnosis." (PMID 41466916, 2025). "Detailing the comparative analysis of the BRCA1 and BRCA2 genes in humans and dogs indicates these genes’ critical roles in maintaining genomic integrity and preventing cancer in species." (PMID 40004231, 2025). "RTx-284 also demonstrated strongsynergy with multiple PARPi in MDA-MB-436 and PE01 cancer cell linesharboring BRCA1 and BRCA2 pathogenic mutations, respectively." (PMID 41124685, 2025). "This fact is noteworthy since most of the significant cancer-related results from the PheWAS analyses were tied to BRCA2." (PMID 39799398, 2025).
cancer (continued). "Our findings make the case that APOBEC3B is not merely a passive mutator but a major orchestrator of replication stress-induced genomic instability in BRCA2-mutant cancers." (PMID 41162355, 2025). "There are recommended measures for prevention and earlier diagnosis of cancers in patients identified as BRCA1 and BRCA2 PGV carriers, which are the most common cancer-predisposing PGVs." (PMID 40123843, 2025). "Thanks to this effect, PARPis quickly became a novel class of anti-cancer drugs, first demonstrating efficiency in treating HR-deficient tumors with a BRCA1 and BRCA2 mutation." (PMID 40616061, 2025). "We successfully identify cancer-associated genes such as BRCA1, BRCA2, PALB2, and TCEAL4, all exhibiting the sought-after expression patterns." (PMID 40983914, 2025). "Some FA genes, such as FANCD1 [BRCA2] and FANCJ [BRIP1], act as cancer predisposition genes in a monoallelic autosomal dominant manner." (PMID 40358701, 2025). "In conclusion, utilizing this large population based cohort, we implicated the risk of BRCA2 PVs for classic HBOC cancers and six other types of cancer and demonstrated the interplay between BRCA2 and PGS for cancer risk." (PMID 40462315, 2025). "Most individuals carrying cancer susceptibility gene variants, such as BRCA1, BRCA2, and ATM, are heterozygous for a single pathogenic variant." (PMID 40777133, 2025). "Heterozygous carriers of pathogenic variants in FA pathway genes—most notably FANCD1/BRCA2 and FANCN/PALB2—are at increased risk for various cancers, particularly breast, ovarian, and pancreatic malignancies." (PMID 41155398, 2025). "Clinical and pathogenic characteristics of cancers with GDH for BRCA1 and BRCA2 depend on the genes somatically mutated in wild alleles." (PMID 40601170, 2025). "PARP inhibitors (PARPis) are drugs that exploit synthetic lethality to target cancer cells that have defects in DNA repair pathways, such as those caused by mutations in BRCA1 or BRCA2 genes." (PMID 39996890, 2025). "We acknowledged the low number of BRCA2 mutation carriers in our collection as well as the differences between BRCA1- and BRCA2-driven cancers, and intentionally limited the study to the BRCA1 gene." (PMID 41374957, 2025). "HBOC is a condition that increases the probability of developing breast, ovarian and other types of cancer, such as pancreatic and prostate cancer, due to the presence of germline mutations in genes of greater susceptibility, such as BRCA1 or BRCA2." (PMID 40259910, 2025). "It is estimated that <5% of BRCA1 and BRCA2 carriers among women with BC are identified in Asia due to major gaps in the availability of cancer-specialised genetic counselling (GC) and access to funded genetic testing (GT) in this region." (PMID 40626014, 2025). "Both BRCA1 and BRCA2 play pivotal roles in the repair of double‐strand breaks (DSBs) in DNA, which is crucial for preventing genomic instability and cancer development." (PMID 40523654, 2025). "We are initiating a feasibility study that employs a germline cancer genomic panel of 30–80 high-risk cancer genes, such as BRCA1 and BRCA2, to identify individuals with pathogenic variants." (PMID 40552262, 2025). "These two papers are foundational works in the field, as they were the first to elucidate the role of BRCA2 in regulating DNA repair and to demonstrate how the impairment of this function in cancer cells can be leveraged for therapeutic purposes." (PMID 40421223, 2025). "This study demonstrates the value of population-scale EHR linkages, and that survivors of BC carrying BRCA1/BRCA2 PVs are at elevated cancer risks." (PMID 39475295, 2025). "It is necessary therefore to evaluate empirically the underlying distribution of the relevant cancer risk factors for BRCA1 and BRCA2 PV carriers." (PMID 40399999, 2025).